ATP1A3 (ATPase Na+/K+ transporting subunit alpha 3)
Diseases named in the same sentence as ATP1A3 in open-access papers (continued):
Sharing a sentence is not in itself a finding about the gene and the disease.
cancer (4 papers, 2020 to 2023). A tumor composed of atypical neoplastic, often pleomorphic cells that invade other tissues. "Mechanistic research further indicated that point mutations in ATP1A3 could exert decisive effects on the anti‐cancer activity and the chemosensitizing effect of CS‐6." (PMID 31746080, 2020). "To further validate our data, we tested the protein expression of the ATP1A gene family members (including ATP1A1, ATP1A2, and ATP1A3) in cancer and paracancerous tissue samples of six patients with OSC." (PMID 32684846, 2020). "Overall, ATP1A3 could be important for the anti‐cancer effect as well as the chemosensitizing effect of CS‐6." (PMID 31746080, 2020). "In the future, new techniques, such as Ala‐scanning, could be further used to determine the active sites on the ATP1A3 protein to accelerate the discovery of various other anti‐cancer drugs." (PMID 31746080, 2020). "We expected that the functional interaction between ATP1A3 and AQP4 might mediate the anti‐cancer effect of CS‐6 and the chemosensitizing effect of CS‐6 on TMZ." (PMID 31746080, 2020). "Both ATP1A3 and ATP1A4 are sodium pump subunits in mammals, and thus, we proposed that these two proteins might be involved in the anti‐cancer effects of CS‐6 in GBM cells." (PMID 31746080, 2020). "Studies regarding the differential expression of ATP1A3 in cancer tissue have not been found." (PMID 36900348, 2023). "Unfortunately, we could not conclude that ATP1A3 is the only target of CS‐6 in GBM because other captured proteins might also be involved in the anti‐cancer activity of CS‐6." (PMID 31746080, 2020). "Currently, the correlation between ATP1A3 and AQP4 in human cancers and their mechanistic interactions have not been addressed." (PMID 31746080, 2020). "We first examined the effect of CS‐6 on ATP1A3 expression in our panel of GBM cell lines, and we found that in U87, U251 and U118 cells, CS‐6 significantly increased ATP1A3 expression, while this effect was not as obvious in human normal SVG‐p12 cells as in cancer cells." (PMID 31746080, 2020).
neurodegenerative disease (4 papers, 2018 to 2023). A disorder of the central nervous system characterized by gradual and progressive loss of neural tissue and neurologic function. "Second, while dysfunctions in ubiquitous ATP1A1 and neuron-specific ATP1A3 have been predominantly linked to neurodevelopmental disorders, their role in regulating miR-132 may suggest potential underexplored functions in neurodegenerative diseases." (PMID 37989753, 2023). "In addition, studies into neurodegenerative disease mechanisms have shown ATP1A3 deficits in a number of cases." (PMID 30623173, 2018).
neurodevelopmental disorder (3 papers, 2021 to 2025). A behavioral and cognitive disorder with onset during the developmental period that involves impaired or aberrant development of intellectual, motor, or social functions. "AHC, initially described by Verret and Steele in 1971, represents a rare neurodevelopmental disorder primarily caused by de novo ATP1A3 pathogenic variants." (PMID 40217402, 2024). "Alternating hemiplegia of childhood is a rare neurodevelopmental disorder caused by ATP1A3 mutations." (PMID 34396101, 2021).
genetic disorder (2 papers, 2017 to 2026). "It is an extremely rare genetic disorder related to ATP1A3 gene mutations." (PMID 28900444, 2017).
psychiatric disorder (2 papers, 2021 to 2022). A disorder characterized by behavioral and/or psychological abnormalities, often accompanied by physical symptoms. "Variants in ATP1A3 produce a wide spectrum of AD neurological and psychiatric disorders, ranging from infantile to adult onset." (PMID 35326432, 2022).
cardiovascular diseases (1 paper, 2024). "Also up-regulated was the Na+-K+ exchanger Atp1a3 whose mutations are related to several neurological and cardiovascular diseases." (PMID 38534766, 2024).
kidney disease (1 paper, 2025). "While limited research has explored Atp1a3 in kidney disease, its expression in immune cells suggests a role in immune activation and regulation." (PMID 40305204, 2025).
ATP1A3 also shares sentences with these, for which no sentence is quoted: optic atrophy (26 papers); Areflexia (25); Pes cavus (24); Ataxia (21); sensorineural hearing loss (19); microcephaly (4); autism spectrum disorder (3); dystonia 12 (3); episodic ataxia (3); hemiplegia (3); infection (3); Intellectual disability (3); Apnea (2); biotinidase deficiency (2); bipolar disorder (2); Choreoathetosis (2); Darier disease (2); Dyskinesia (2); early infantile epileptic encephalopathy (2); early-onset epilepsy (2); epilepsy syndrome (2); generalized genetic epilepsies (2); medulloblastoma (2); metabolic disorder (2); migraine (2); mood disorder (2); Myoclonus (2); polymicrogyria (2); abetalipoproteinemia (1); adrenoleukodystrophy (1).
A further 80 diseases each share a sentence with ATP1A3 in 1 paper.